PHGDH (phosphoglycerate dehydrogenase)
Diseases named in the same sentence as PHGDH in open-access papers (continued):
Sharing a sentence is not in itself a finding about the gene and the disease.
cancer (continued). "As PHGDH is thought to be the rate-limiting step of serine synthesis and important for the proliferation of PHGDH-amplified cancer cell lines, several inhibitors have been developed." (PMID 33669382, 2021). "The enhanced expression of PHGDH activates serine synthesis and then promotes cancer growth and progression." (PMID 34957102, 2021). "Lastly, some genes (HMGN5, IRS1, PHGDH, MXRA5, GOLIM4, and SFRP2) are associated with the development of multiple cancer types." (PMID 33924951, 2021). "As the rate-limiting enzyme of the serine biosynthesis pathway, PHGDH is overexpressed in various types of cancer, and appears to be a promising target for cancer therapy." (PMID 34957102, 2021). "The significant effects of NCT-503 combined with perhexiline in vivo, with minimal toxicity and dramatic tumor control, show that PHGDH inhibition combined with mTORC1-signaling inhibition are a promising dual therapy in PHGDH-high cancers." (PMID 33503424, 2021). "Several small molecule inhibitors of PHGDH that inhibit de novo serine synthesis and retard the growth of cancer cells that are dependent on this pathway have been generated." (PMID 33446657, 2021). "Some cancers acquire an amplification or overexpression of PHGDH – the first step in the SSP – and these cells tend to be less affected by serine starvation." (PMID 33446657, 2021). "It has been reported that PHGDH is upregulated in some cancers derived from distinct histology and functions as an oncogenic gene." (PMID 34178629, 2021). "The commitment step for serine biosynthesis is oxidation of 3PG by phosphoglycerate dehydrogenase (PHGDH) to 3-hydroxyphosphopyruvate, and this enzyme is elevated in a number of cancers, including breast." (PMID 34209132, 2021). "PHGDH inhibition has a cytostatic effect, consistent with previous publications in other PHGDH-high cancers." (PMID 33503424, 2021). "This study has explored the efficacy of a combination of serine/glycine depletion with PHGDH inhibition to inhibit cancer cell growth." (PMID 33446657, 2021). "It is clear that inhibition of cancer proliferation with PHGDH inhibitors is a promising therapeutic avenue." (PMID 33931592, 2021). "They observed a significant positive correlation between PHGDH and Oct4 expressions both in vitro in Embryonic Carcinoma Stem-Like Cells and in Cancer Stem-Like Cells from patients." (PMID 34072080, 2021). "Previous studies have observed that PHGDH inhibition induced autophagy in carcinoma cells but have attributed that effect to an mTOR-independent mechanism because of the lack of response to rapamycin treatment." (PMID 33503424, 2021). "PKUMDL-WQ-2101 and NCT-503 have been widely used in in vitro and in vivo research to interrogate the role of PHGDH and serine metabolism in normal and cancer cells." (PMID 33511334, 2020). "Increased PHGDH expression has been demonstrated to not only promote cancer growth and proliferation, but also drive secondary tumour formation and metastasis." (PMID 33511334, 2020). "Recently, it has been reported that PHGDH is amplified or overexpressed in various types of cancers." (PMID 32386122, 2020). "When cancer cells with elevated PHGDH expression are treated with high doses of NCT-503, cellular proliferation is attenuated and, in some cases, cell death is observed." (PMID 33511334, 2020). "Of these, the serine biosynthetic pathway is of interest because the rate limiting enzyme, 3-phosphoglycerate dehydrogenase (PHGDH), is highly expressed in a variety of cancers and contributes to drug resistance." (PMID 33511334, 2020). "Downregulated PARKIN in cancer suppresses ubiquitination of PHGDH and enhances its stability and protein level, thereby activating serine synthesis and promoting cancer progression." (PMID 33004065, 2020). "Through the biology of PHGDH, mechanisms of resistance to current cancer treatments, as well as proposed novel treatments, are identified." (PMID 33511334, 2020).
cancer (continued). "The development of more effective PHGDH inhibitors to investigate the serine synthesis pathway in cancer biology hence remains necessary." (PMID 31979167, 2020). "This review will investigate the role of PHGDH in normal biological processes, leading to the role of PHGDH in the progression of cancer." (PMID 33511334, 2020). "d-3-phosphoglycerate dehydrogenase (PHGDH), which encodes the first enzyme in serine biosynthesis, is overexpressed in human cancers and has been proposed as a drug target." (PMID 32549981, 2020). "Beyond NRF2 regulation, SSP activity is increased in diverse cancer types as a consequence of PHGDH amplification, overexpression, and posttranscriptional regulation." (PMID 33080927, 2020). "Given the increased expression of PHGDH in a variety of cancers, the single-agent inhibition of PHGDH seems to be a promising prospect for cancer therapy." (PMID 33511334, 2020). "Over recent years, an increasing number of studies have focused upon PHGDH in cancer research, which is found to exhibit elevation and controlled flux throughout the serine biosynthetic pathway in cancer cells." (PMID 32664979, 2020). "Given that increased PHGDH contributes to tumorigenesis, the role of PHGDH in cancer resistance is multi-faceted." (PMID 33511334, 2020). "Current and future research on the adaptive mechanisms of resistance to PHGDH is needed to harness the upregulation of PHGDH in cancer." (PMID 33511334, 2020). "NCT-502/-503 have been shown to reduce serine biosynthesis and impair PHGDH-dependent cancer growth both in vitro and in vivo." (PMID 32824193, 2020). "Due to its central biological importance, cancer cells often have high demand for serine and thus activate serine biosynthesis mainly by upregulating PHGDH expression." (PMID 32824193, 2020). "Identifying increased PHGDH expression as a resistance mechanism for a variety of cancer therapeutics offers the opportunity to combine PHGDH inhibition with small molecule therapeutics." (PMID 33511334, 2020). "In particular, cancers are capable of developing resistance to chemotherapies that induce apoptosis through increased ROS by increasing PHGDH, as PHGDH generates the necessary metabolic precursors for antioxidant and ROS scavenging activity." (PMID 33511334, 2020). "In this article, we reviewed the type, structure, expression and inhibitors of PHGDH, as well as the role it plays in cancer and tumor resistance to chemotherapy." (PMID 32226297, 2020). "PHGDH activity is increased in many cancer cells as a consequence of genomic amplification, transcriptional upregulation, posttranslational modification, and allosteric regulation." (PMID 32549981, 2020). "While the contribution of PHGDH and serine to cancer cell metabolism has been well studied, less is known about the importance of PHGDH in normal tissues." (PMID 32549981, 2020). "Cancer cells with increased PHGDH activity are more dependent on PHGDH for proliferation, suggesting PHGDH is an attractive target for cancer therapy." (PMID 32549981, 2020). "It is known that cancer cells have a higher capacity for de novo serine synthesis via the PHGDH pathway." (PMID 32471029, 2020). "We previously reported the discovery of compound 1, a PHGDH inhibitor with robust cancer cell inhibition." (PMID 31979167, 2020). "Despite the interest in targeting PHGDH and the increasing number of reported inhibitors, the weak in cellulo and in vivo efficacy of the inhibitors hamper the understanding of the role PHGDH plays in cancer progression." (PMID 31979167, 2020). "The combination of PHGDH inhibition with inhibitors of these pro-survival metabolic adaptations should therefore yield synergistic and dramatic results in PHGDH-high cancers." (PMID 33511334, 2020). "Overexpression of PHGDH drives numerous pathways that are particularly useful for the initiation and progression of cancer." (PMID 33511334, 2020).
cancer (continued). "High PHGDH expression is observed in select cancer cells and in some cases is necessary for proliferation and survival." (PMID 31331318, 2019). "SSP represents a metabolic vulnerability of cancer cells under drug treatment while targeting SSP through PHGDH inhibitors is an attractive therapeutic approach for TKI resistant HCC." (PMID 31615983, 2019). "Future studies which involve the modification of PHGDH inhibitors to increase its bioavailability will popularize the usage of PHGDH inhibitors as a cancer therapy." (PMID 31615983, 2019). "Both NCT-503 and CBR-5884 displayed higher growth inhibitory effects in cancer cells which express a high level of PHGDH especially under extracellular serine-depleted condition." (PMID 31615983, 2019). "Given the importance of PHGDH in cancer metabolism and the growing interest in repurposing DSF for cancer therapy, we set out to examine structure–activity relationships (SAR) in a series of DSF analogs and to elucidate its mechanism-of-action." (PMID 30894617, 2019). "Using immunoblotting, we found that the average enzyme expression levels vary significantly among these cell lines; Several cancer cell lines expressed PHGDH at high levels, while other cell lines displayed low to minimal PHGDH expression." (PMID 29925909, 2018). "Next, we wished to understand the clinical relevance of the correlation between PHGDH and stemness in human cancers." (PMID 30250195, 2018). "In order to extend the reported analyses into other cancer types, we analysed PHGDH protein levels by Western blot in a panel of 50 different cell lines belonging to ten different cancer types." (PMID 29568346, 2018). "In line with this role, the SSP is often highly active in cancer cells and 3-phoshoglycerate dehydrogenase (PHGDH), the first and rate-limiting enzyme in this pathway, is frequently upregulated in different cancers." (PMID 30456204, 2018). "It is also notable that we identified over 10 cancer-related genes (including PHGDH, CCND1, IGFBP-2, XAGE1B/E, CYP4F22, RBM11, ORAOV1, MDK, UGT3A5, SSX5, FBL, NKX2) potentially overexpressed in EFT tumors." (PMID 30093970, 2018). "Taken together, these data highlight a therapeutic implication for PHGDH and stemness in cancer, and further advocate for the need to understand the mechanistic aspects of this clinically relevant association." (PMID 30250195, 2018). "The initial target validation, performed in in vitro and in vivo knockdown models, points towards PHGDH as a promising target in cancer." (PMID 29568346, 2018). "3-Phosphoglycerate dehydrogenase (PHGDH) has recently been identified as an attractive target in cancer therapy as it links upregulated glycolytic flux to increased biomass production in cancer cells." (PMID 29568346, 2018). "PHGDH has recently been shown to be a potential therapeutic target in cancer types that overexpress PHGDH." (PMID 29568346, 2018). "It has also been demonstrated that high PGAM1 expression in cancer cells maintains serine biosynthesis through activation of phosphoglycerate dehydrogenase (PHGDH), the first enzyme of the serine biosynthesis pathway, which is allosterically activated by 2PG." (PMID 28531108, 2017). "Amplification of PHGDH de-sensitizes tumors to exogenous serine levels but also represents a vulnerability point for potential cancer treatment." (PMID 29312889, 2017). "The authors demonstrated that deprivation of glucose or glutamine, two major nutrition sources for cancer cells, led to the enhanced c-Myc expression, which in turn activated the expression of three key enzymes of serine synthesis, PHGDH, PSAT1 and PSPH." (PMID 28177894, 2017). "PHGDH inhibition in highly proliferating cancer cells addicted to de novo serine synthesis has the potential to deplete one-carbon units in the mitochondrial folate cycle, thus lowering the mitochondrial NADPH pool and inducing oxidative stress." (PMID 28649560, 2017).
cancer (continued). "It is also possible that PHGDH inhibition in serine synthesis-addicted cancer cells shifts the equilibrium of the SHMT2 reaction toward serine, thus inverting the mitochondrial folate cycle and blocking NADPH production in mitochondria." (PMID 28649560, 2017). "PHGDH, the first and rate-limiting enzyme of the SSP, is often overexpressed in cancer and has been linked to tumorigenesis as well as poor diagnosis in different cancers, identifying PHGDH as an interesting pharmaceutical target." (PMID 28855983, 2017). "On the contrary, PHGDH-overexpressing cancer cells are addicted to de novo serine synthesis, whose inhibition leads to the blockade of exogenous serine incorporation into purines." (PMID 28649560, 2017). "The upregulation of SHMT2 in cancer correlates with the increased expression of phosphoglycerate dehydrogenase (PHGDH), the enzyme that catalyzes the first, limiting, step in the de novo serine synthesis pathway." (PMID 28649560, 2017). "Increased expression of PHGDH and other serine biosynthesis pathway enzymes is found in other cancer contexts as well, with evidence that c-Myc, ATF4, and the lysine methyltransferase G9A increase PHGDH expression via transcriptional and epigenetic mechanisms." (PMID 25926973, 2015). "Though on average the concentration of PHGDH was lower, in many cancer cell lines, the concentration of PHGDH was comparable or even higher than that of PGAM in some cases." (PMID 25621879, 2015). "PHGDH has been proposed as a potential drug target in cancer, and the impact of an epitope tag has practical implications for designing screens for small-molecule PHGDH inhibitors." (PMID 25926973, 2015). "Recently, the essential role of the serine biosynthesis pathway in metabolic reprogramming in cancer has been recognized, and PHGDH was found to be overexpressed and to contribute to tumor cell growth in a significant subset of human cancers." (PMID 26372729, 2015). "Addition of an N-terminal epitope tag to PHGDH alters enzyme structure, reduces catalytic activity, and abrogates its ability to support proliferation of PHGDH-dependent cancer cells." (PMID 25926973, 2015). "In terms of using PHGDH as a potential therapeutic target, one would need to establish a significant difference between the requirement of the enzyme's activity in cancer and in normally proliferating cells." (PMID 25574168, 2014). "Both studies published in mid-2011 report that the gene encoding PHGDH is amplified in a significant subset of human tumors and underscore that diversion of glycolytic intermediates into the serine biosynthetic pathway may contribute to tumorigenesis in cancer cells." (PMID 25574168, 2014). "PHGDH was expressed in 68.1% of the ER-negative cancers in comparison with 18.5% in the ER-positive cancers and was associated with high histologic grading, ER negativity, PR negativity, and high Ki-67 LI, which are known as poor prognosticators." (PMID 24979213, 2014). "Among a number of metabolic enzymes, one key enzyme for serine biosynthesis, PHGDH, has been reported in recent cancer biology studies." (PMID 23229761, 2013). "The different effects of PHGDH knockdown on tumor initiation and maintenance suggest that the requirement of PHGDH in cancer is context-dependent or tumor stage dependent." (PMID 24318446, 2013). "PHGDH knockdown in these cells leads to a reduction of serine synthesis and impairment of cancer cell proliferation." (PMID 24318446, 2013). "In some cancer cells, a large amount of glycolytic carbon is diverted to serine and glycine through phosphoglycerate dehydrogenase (PHGDH)." (PMID 22988443, 2012). "The PHGDH gene is found amplified in several tumors, while ectopic expression of PHGDH predispose to tumorigenesis and inhibition of PHGHDH expression reduces proliferation of cancer cell lines." (PMID 22988443, 2012). "Targeting PHGDH in cancer therapy reveals key paradoxes and corresponding resolution strategies." (PMID 41486146, 2026).
cancer (continued). "The small molecule inhibitor, NCT‐503, could potentially inhibit PHGDH, which is useful for studying serine production via PHGDH in various cancer types." (PMID 40956032, 2025). "PHGDH overexpression is frequently observed in breast, lung, colorectal, melanoma, and pancreatic cancers, where it promotes tumor progression, aggressiveness, and poor prognosis by supporting pathways critical for cancer proliferation." (PMID 40076506, 2025). "Because PHGDH expression is important for proliferation in serine depleted conditions, we first assessed PHGDH protein expression across the different cancer cells to examine how well this explained environmental serine dependence." (PMID 40654753, 2025). "Increased PHGDH expression levels are also observed in other types of cancers." (PMID 40265021, 2025). "However, in contrast to its upregulation in certain cancers, PHGDH expression is downregulated in some tumor types, particularly in metastatic cancers due to its metabolic heterogeneity." (PMID 40475404, 2025). "Notably, PHGDH protein level is a dynamic feature that can be modulated over time during cancer progression." (PMID 40640948, 2025). "As a potential target, exploring whether PHGDH promotes HCC progression through non-canonical functions from the perspective of RNA metabolism regulation may provide additional strategies for anti-cancer drugs that target PHGDH." (PMID 40681503, 2025). "PHGDH is frequently amplified, especially in aggressive cancer types." (PMID 41462671, 2025). "Glucose deprivation in cancer cells induces expression of the lncRNA, Linco156 that subsequently serves as a ceRNA to sequester miRNA inhibitors (miR107/103a-3p) of the phosphoglycerate dehydrogenase (PHGDH) gene." (PMID 39761690, 2025). "Besides these metabolic roles, PHGDH is emerging as a driver of cancer aggressiveness by modulating different mechanisms." (PMID 40640948, 2025). "Inhibiting PHGDH or other enzymes in the serine–glycine pathway reduces the availability of one-carbon units required for nucleotide synthesis, impairing DNA repair and increasing the sensitivity of cancer cells to radiotherapy." (PMID 39796683, 2024). "The authors call for more research to fully understand PHGDH’s role in cancer and to develop effective inhibitors that could be used in clinical settings." (PMID 38945960, 2024). "Consequently, PHGDH inhibition has demonstrated efficacy in suppressing the growth of cancer cells with PHGDH amplification or overexpression, leading to the identification of several PHGDH inhibitors." (PMID 38945960, 2024). "Targeting PHGDH as a treatment strategy for cancers with PHGDH overexpression may strongly inhibit cancer progression, indicating that high expression of PHGDH in tumors is a critical therapeutic target." (PMID 38710705, 2024). "Owing to its unique function, PHGDH might be considered a promising target in cancer therapy, since it has been found overexpressed in several tumors." (PMID 38115544, 2024). "Therefore, we performed further analysis of PHGDH, one of the partially metabolized enzymes known to be dysregulated in cancer." (PMID 38577610, 2024). "PHGDH is frequently overexpressed in tumors through mechanisms such as gene amplification, transcriptional regulation, degradation, and alterations in stability, thereby promoting cancer progression." (PMID 39223162, 2024). "Researchers suggest that targeting PHGDH could be a promising strategy for cancer treatment, potentially improving outcomes for patients with tumors that overproduce PHGDH." (PMID 38945960, 2024). "In recent years, the importance of PHGDH in cancer is increasingly being recognized." (PMID 39207107, 2024). "Given the important role of the CCL2-CCR2 chemokine signaling pathway in monocyte/macrophage recruitment in tumor models, we hypothesized that PHGDH depletion could impair macrophage migration toward cancer cells." (PMID 38409249, 2024).